CRY1 (cryptochrome circadian regulator 1)
Diseases named in the same sentence as CRY1 in open-access papers (continued):
Sharing a sentence is not in itself a finding about the gene and the disease.
cancer (61 papers, 2010 to 2025). A tumor composed of atypical neoplastic, often pleomorphic cells that invade other tissues. "The observation that CRY1 is associated with poor outcome in metastatic PCa, coupled with linkage of the newly identified CRY1 cistrome to cancer-promoting pathways, suggests that CRY1 plays roles distinct from circadian regulation in PCa." (PMID 33452241, 2021). "We further investigated the association of candidate cancer-related genes clock (Bmal1 and Cry1/2) genes." (PMID 31523185, 2019). "The SNPs or deregulation of CRY1 and/or 2 are associated with increased susceptibility and mortality to several type of cancer." (PMID 28177907, 2017). "Next, we investigated the effects of Cry1 manipulation (through gain-of-function and loss-of-function) on the proliferation of cancer cells." (PMID 23626715, 2013). "Remarkably, Bmal1 heterozygotes and Cry1-deficient mice, both of which maintain circadian rhythms even in constant darkness, were also more cancer-prone than the controls." (PMID 21566258, 2011). "We found that when kept in 24 hour alternating light-dark conditions (24hr LD cycles), mice deficient in Bmal1 (Bmal1+/−), Cry1 and Cry2 (Cry1−/−;Cry2−/−), Per1 and Per2 (Per1−/−;Per2m/m) or Per2 alone (Per2−/−) were all cancer-prone." (PMID 20539819, 2010). "CRY1 is one of the transcriptional coregulators associated with circadian rhythm and has recently been reported to regulate the expression of genes required for HR in cancer cells." (PMID 38420012, 2024). "However, the GT genotype of the CRY1 gene was the genetic variant with the lower risk of suffering cancer, as well as for those subjects carrying CC genotype of the CRY2 gene having an even lower risk." (PMID 30873119, 2019). "In addition to this, CRY1 is involved in cellular DNA damage repair, and its depletion enhances DNA damage in cancer cells, whereas CRY1 expression is reduced in the presence of Yes-associated protein (YAP) silencing or TEA domain transcription factor (TEAD) inhibition." (PMID 39139571, 2024). "cry1 levels were increased in cancer compared to adjacent tissue, and this difference achieved the level of significance only in older patients." (PMID 40868120, 2025). "The KD of CRY1 restores the ability of paclitaxel to induce cellular senescence in these cancer cells." (PMID 41264145, 2025). "This discordance between NR1D1 and NR1D2 is a possible source of the small amplitudes in RRE-targets NPAS2, NFIL3, and CRY1 in the cancers." (PMID 40424435, 2025). "Recent research showed that DNA damage stabilized CRY1, and the stabilized CRY1 temporally regulated the expression of genes required for HR in cancer cells." (PMID 38420012, 2024). "CRY1 is also a core circadian gene, modulates the circadian rhythm and promotea the development of cancer." (PMID 37323834, 2023). "CRY1 expression is correlated to poor patient survival.CRY1 is stabilized by DNA damage in cancer and regulates homologous recombination." (PMID 39282509, 2023). "Mice with genetic disruptions of Per2, Bmal1, Cry1, and Cry2, which are regulatory factors of the circadian clock, spontaneously developed cancer in multiple organs, including the liver and ovaries." (PMID 37524704, 2023). "Beyond its importance as a repressor of the TTFL in circadian clocks, CRY1 has been found to regulate metabolic oscillations and participate in DNA damage response and cancer." (PMID 35471909, 2022).
cancer (continued). "A recent study using a cancer cell line model has also shown that CRY1 protein remains nuclear at all circadian phases and at markedly higher abundance than its partner protein PER2." (PMID 35285799, 2022). "DNA damage stabilizes CRY1 in cancer (in vitro, in vivo, and human tumors ex vivo), which proves critical for efficient DNA repair." (PMID 33452241, 2021). "Gene set enrichment analysis (GSEA) revealed that CRY1 governs transcriptional programs of cancer relevance, including those involved in DNA replication, cell cycle regulation, and multiple DNA repair processes." (PMID 33452241, 2021). "The present study reveals the first genome-wide insight into CRY1 function in human carcinomas and provides the basis to discern the molecular underpinnings(s) by which CRY1 impacts cancer outcomes." (PMID 33452241, 2021). "Cry1 mRNA overexpression has been previously associated with poor OS in CRC, mainly in elderly subjects, female patients and cancers located at the transverse colon." (PMID 34440171, 2021). "Given the identification of CRY1 as an androgen-regulated gene of cancer relevance, the mechanism through which CRY1 influences cancer outcomes was assessed." (PMID 33452241, 2021). "While the mechanisms by which AR specifically binds to the CRY1 locus and induces CRY1 expression remain undefined, these findings identify a target of AR-regulation that promotes cancer phenotypes." (PMID 33452241, 2021). "As shown, ~70% ablation of CRY1 protein was achieved after shRNA induction (left), subsequent to which the first whole-transcriptome analysis of CRY1 was assessed in human carcinomas (right), with strong consistency amongst biological replicates." (PMID 33452241, 2021). "Cry1 and Cry2 acted as transcriptional regulators and checkpoint proteins for cancer cell proliferation and cell cycle control." (PMID 32437452, 2020). "The expression analysis results indicated alterations in cancer-related genes in Cry1/2 double knockout mice exposed to CJL." (PMID 31523185, 2019). "We compared expression levels of candidate cancer genes from Bmal-/- and Cry1/2 knock mice with C57BL/6 mice." (PMID 31523185, 2019). "Diverse circadian genes are known to be correlated with poor prognosis when aberrantly overexpressed in several cancers, including CRY-1." (PMID 28884705, 2018). "Our finding is in agreement with a previous animal study showing that the decreasing CRY1 expression renders animals more sensitive to platinum-based ACT cancer therapy." (PMID 26927666, 2016). "Functional assay suggested rs1056560 genotypes significantly affect CRY1 expression in cancer cells." (PMID 26927666, 2016). "It is necessary to collect more cases in the future to validate the relationship of CRY1 expression and GC cancer stage." (PMID 24708606, 2014). "We divided the patients into earlier stages (stages I and II) and more advanced stages (stages III and IV) for correlation analysis with circadian clock gene expression and found that CRY1 expression was upregulated in more advanced cancer stages (p < 0.05)." (PMID 24708606, 2014). "Several previous studies have compared the expression levels of Cry1 between cancer tissue and adjacent normal mucosa." (PMID 23626715, 2013). "This study also found higher Cry1 expression in the tumor mucosa of cancers located in distal colorectal segments." (PMID 23626715, 2013). "We attempted to test whether CRY1 could suppress the growth of cancer cells by decreasing glycolysis." (PMID 38199564, 2024). "CRY1, in particular, is also a known regulator of cell proliferation and DNA repair and has been shown to inhibit nuclear receptors involved in certain cancers." (PMID 39587706, 2024). "Whether CRY1 could be a novel target for cancer cell metabolism needs to be further evaluated in vivo." (PMID 38199564, 2024).
cancer (continued). "This suggests that Cry2 may play a more dominant role than Cry1 in altering cancer-related signaling pathways." (PMID 37024472, 2023). "Since M47 decreases CRY1 and enhances the level of Per2 both in the cell line and in vivo, we hypothesized that M47 could be a useful molecule for cancer treatment by promoting apoptosis." (PMID 36347873, 2022). "Although circadian clock disruption is related to various cancer types, the loss of Cry1 and Cry2 caused an unexpected effect on cancer and did not aggravate the radiation-induced tumor growth and mortality." (PMID 36347873, 2022). "Pathway analysis, functional molecular studies, and biological validation herein revealed that CRY1 governs a discrete network of transcriptional programs of cancer relevance, including regulation of DNA replication, cell cycle control, and multiple DNA repair processes." (PMID 33452241, 2021). "The impact of the CRY1 amplicon in tumor behavior is a fertile area for future investigation, as co-amplification in this region of 12q23 is frequently observed in concert with adjacent genes of potential relevance to cancer." (PMID 33452241, 2021). "Thus, observations in multiple tissues identify CRY1 activities beyond canonical circadian function, which have yet to be investigated in human carcinomas." (PMID 33452241, 2021). "Crem has been previously implicated as a key player in tumor regulation/suppression 62,63, hence its altered expression also indicates that CJL can increase cancer risk if Bmal1 is nonfunctional while the non-functionality of Cry1/2 has an opposite effect." (PMID 31523185, 2019). "Importantly, 4T1 cancer cells disrupt expression patterns of Bmal1, Cry1, and Clock in the liver, a possible upstream of the decreased OXPHOS expression." (PMID 28388556, 2017). "In addition, lower CRY1 mRNA levels were observed in patients in the age range of 62-74 years (p = 0.018), in female patients (p = 0.003) and in cancers located at the transverse colon (p = 0.008)." (PMID 26768731, 2016). "The increased expression of CRY1 in the cancer cells was three times higher than in normal mucosa." (PMID 27465361, 2016). "CRY1 expression may be considered a useful biomarker for determining cancer stage and prognosis in GC patients." (PMID 24708606, 2014). "From a cancer biology standpoint we next wanted to test whether deregulated CRY1 expression may also be observed in other lymphoid malignancies than CLL." (PMID 22470559, 2012). "As CRY1 has been previously shown to undergo aberrant DNA methylation events in various human cancers, we then examined whether epigenetic silencing could explain CRY1 mRNA expression differences in CLL." (PMID 22470559, 2012). "Furthermore, CLOCK and CRY1 might possess tumorigenic characteristics, and this is substantiated by whole-genome expression microarray studies that found expression of multiple cancer-related transcripts to be modified after CLOCK gene knockdown." (PMID 39587706, 2024). "Recent genome-wide studies reveal that CRY1, which regulates DNA repairing and cell proliferation, has relevance to advanced disease as an AR-regulated and pro-tumorigenic factor that promotes DNA repair and the survival of cancer cells via AR binding to the CRY1 locus." (PMID 36291899, 2022). "Furthermore, CRY1 and CRY2 isoforms have been differentially associated with cancer and may function as pro- or anti-tumorigenic factors depending on the type of cancer." (PMID 35153842, 2022). "Finally, studies here underscore the overall clinical relevance of CRY1 alterations in cancer." (PMID 33452241, 2021). "The E-box regulators BMAL1, CLOCK, CRY1, and PER1, as proteins, play a role in several cancers, and MB should be added to the list of those cancers." (PMID 40002179, 2025).
cancer (continued). "GEPIA was used to understand the messenger (m)RNA expressions of circadian rhythm-related factors in the PER family (PER1, PER2, and PER3), CRY family (CRY1 and CRY2), BMAL1, and CLOCK in different types of cancer." (PMID 36385012, 2022). "Compared with the adjacent normal tissues, the expression of NR1D1, DBP, and BHLHE40 was increased, while the expression of CRY1 and CLOCK was decreased in cancer tissues." (PMID 34977153, 2021). "On the contrary, the expression of PER2, PER3, CRY1, KIAA1737, and BHLHE41 are negatively correlated with the infiltration level of four tumor‐infiltrating lymphocytes in pan‐cancer." (PMID 31927791, 2020). "This regulation suggests a relationship between Cry1/2 and Bmal1 and Prkaa2, Ccnd1and Nf1 in promoting CJL mediated cancer." (PMID 31523185, 2019). "ARNTL2 was one of the most amplified genes found in 16 cancers, followed by RORC in 14 cancers and NR1D1 and CRY1 in 12 cancers each." (PMID 31014368, 2019). "Among 716 samples across 29 cancer types, we interestingly observe that most of the negative regulators, such as PER1, PER2, PER3, CRY1, CRY2, and NR1D2, are down-regulated in a wide range of cancers." (PMID 31708917, 2019). "Significantly decreased transcript levels of CRY1, PER2 were observed in Carcinoma ductale and mix types of carcinomas." (PMID 29958276, 2018). "proved that promoters of these clock genes (PER1, PER2, PER3, CRY1 and CRY2) were methylated in a variety of cancer cells, which resulted in their decreased expression." (PMID 27602964, 2016). "We demonstrated that in vitro and in vivo cancer cells after PER1 knockdown, PER2, DEC1, DEC2, CRY1, CRY2 and NPAS2 were significantly down-regulated at the mRNA level, while PER3, TIM, RORα and REV-ERBα were significantly up-regulated." (PMID 27602964, 2016). "Although KL101 did not slow HTR-8 migration, studies in cancer cell lines have shown that down-regulation of CRY1 increases cell migration, indicating CRY1, at least under specific conditions, does regulate cell migration." (PMID 36284122, 2022). "CRY1 has been implicated as a prognostic marker progression and survival in CLL and other types of cancer, however, the role of URAHP, MID1IP1, and CLEC3B has not been explored in CLL." (PMID 34187466, 2021). "Given this new knowledge, it was critical to assess the non-circadian functions of CRY1 in cancer cells." (PMID 33452241, 2021). "The two datasets with the highest ΔCCD (>50% higher than any ΔCCD we observed in human cancer) were those in which the knockout mice lacked not one, but two components of the clock (Cry1 and Cry2 in GSE13093; Nr1d1 and Nr1d2 in GSE34018)." (PMID 29404219, 2018). "Primary or subgroup meta-analysis for the SNPs concerning all the other clock genes (ARNTL, CRY1, CSNK1E, NR1D1, TIMELESS) considered in this study were found to be not statistically significantly associated with cancer risk." (PMID 28177907, 2017). "This study demonstrates that the down-regulation of PER1 in cancer cells can result in the robust up-regulation of PER3, TIM, RORα and REV-ERBα transcripts, while the expression of PER2, DEC1, DEC2, CRY1, CRY2 and NPAS2 is prominently down-regulated in vitro and in vivo." (PMID 27602964, 2016). "Quantitative real-time PCR result indicated that in vitro and in vivo cancer cells after PER1 knockdown, PER2, DEC1, DEC2, CRY1, CRY2 and NPAS2 were significantly down-regulated at the mRNA level, while PER3, TIM, RORα and REV-ERBα were significantly up-regulated." (PMID 27602964, 2016). "Another study of Cry1-/-Cry2-/- also showed that while these mice were significantly smaller than their WT counterparts, they did not have any obvious malignancies, and they remained reproductively fit." (PMID 20334671, 2010). "Although the oncogenic function of CRY1 has been proposed by regulating DNA repair, the possibility that CRY1 could repress aerobic glycolysis observed in cancer cells could not be excluded." (PMID 38199564, 2024).
cancer (continued). "AR binding at the CRY1 locus was conserved across the cell cycle in PCa with no significant change in mRNA expression 15, indicating that these events are of relevance in mitotically active cancer cells." (PMID 33452241, 2021). "In order to achieve a systematic understanding of circadian clock in cancer, we define a core subset of clock family genes including 7 positive regulators (CLOCK, NPAS2, ARNTL, ARNTL2, RORA, RORB, and RORC) and 7 negative regulators (PER1, PER2, PER3, CRY1, CRY2, NR1D1, and NR1D2)." (PMID 31708917, 2019). "However, Cry1-/-, Cry2-/- transgenic mice do not display a cancer-prone phenotype in response to ionizing radiation exposure." (PMID 20334671, 2010).